EGFR (epidermal growth factor receptor)
Diseases named in the same sentence as EGFR in open-access papers (continued):
Sharing a sentence is not in itself a finding about the gene and the disease.
invasive breast carcinoma (62 papers, 2003 to 2024). A carcinoma that infiltrates the breast parenchyma. "EGFR overexpression has been associated with a poor outcome in invasive breast cancer but very little is reported on DCIS." (PMID 24490077, 2013). "The expression of CK5/6 or EGFR (termed HER1 in his study) was used as the hallmark of the basal-like subtype of invasive breast cancer and was indeed associated with poor survival." (PMID 17088909, 2006). "The epidermal growth factor receptor (EGFR), located on 7p12-13, is an unlikely candidate gene, since the overexpression of EGFR in invasive breast cancer is associated with oestrogen receptor negativity." (PMID 15054466, 2004). "Additionally, EGFR and pEGFR proteins are highly expressed in invasive breast cancer and are associated with worse overall survival rates, while high KLF4 is associated with improved survival outcomes." (PMID 32552913, 2020). "Additionally, we found a high frequency of EGFR mutations in the tumour stroma of these invasive breast carcinomas." (PMID 15841079, 2005). "Overexpression of TLR9 was associated with the induction of epitheliomesenchymal transition (EMT) and deregulation of EGFR signaling in invasive breast carcinomas." (PMID 38850110, 2024). "RNF115 was identified as a binding partner of Rab7, involved in endosomal sorting of EGFR and is highly expressed in invasive breast cancers." (PMID 36281581, 2022). "Elevated phosphorylation levels for the proteins PDK-1, AKT, p70S6K, EGFR, and Stat3 were highly correlated with invasive breast cancers (p < 0.05)." (PMID 34571875, 2021). "For instance, PAR1 transactivates EGFR in invasive breast carcinoma, thereby promoting cellular invasion." (PMID 33932087, 2021). "Overexpression of the epidermal growth factor receptor (EGFR) family member ErbB2 (HER2) drives oncogenesis in up to 25% of invasive breast cancers." (PMID 34439093, 2021). "Regardless of cutoff value selection, basal positivity (positivity for CK5/6 and/or EGFR) has been reported in 15.6% of all invasive breast carcinomas on average." (PMID 32364614, 2020). "Human epidermal growth factor receptor 2 (HER2) is a member of the epidermal growth factor receptor (EGFR) family and is overexpressed in about 30% of invasive breast cancers." (PMID 29651637, 2018). "Using an unbiased approach, we found that mutations in BRAF, EGFR and KIT are significantly more common in this heavily treated population when compared with the cohort of invasive breast carcinoma patients in The Cancer Genome Atlas (TCGA)." (PMID 28247034, 2017). "Immunohistochemical stains for CK5/6, CK14, EGFR and vimentin were performed on 500 invasive breast carcinomas." (PMID 23082819, 2012). "Human epidermal growth factor receptor 2 (HER2), also known as receptor tyrosine-protein kinase ERBB2, belongs to the epidermal growth factor receptor (EGFR) family, and it is one of the most important oncogenes in invasive breast cancer." (PMID 22905152, 2012). "Recent studies and analyses conducted in the present study clearly indicate that EGFR expression serves as the strong prognostic factor in invasive breast cancer." (PMID 20181250, 2010). "In the present study, simultaneous expression of both forms of EGFR emerged as a more promising prognostic marker in invasive breast carcinomas." (PMID 18522728, 2008). "This study examined the expression of EGFR and its activated form, pEGFR, in invasive breast carcinoma." (PMID 18522728, 2008). "The purpose of the present study was to gain further insight into the prognostic significance of EGFR and pEGFR expression in invasive breast cancer." (PMID 18522728, 2008). "Although the activation of TGF‐β signaling and EGFR overexpression are often observed in invasive breast carcinomas and correlated with cancer progression, the detailed mechanism remains unclear." (PMID 29215776, 2018). "In addition, ADAM12 mRNA expression was strongly correlated with the EGFR activation score in 421 breast invasive cancers." (PMID 28148288, 2017).
invasive breast carcinoma (continued). "EGFR has been used as a surrogate marker for basal like invasive breast cancer and for DCIS." (PMID 24490077, 2013). "A three-step immunohistochemical method was applied to paraffin-embedded sections from 154 patients with invasive breast carcinoma in order to detect expressions of the proteins EGFR, pEGFR, oestrogen receptor, progesterone receptor, c-erbB-2, pAkt, VEGFR-1/Flt-1, MMP-14 and uPAR." (PMID 18522728, 2008). "Given that down regulation of AnxA6 in invasive breast cancer cells was accompanied by a decrease in the total and activated EGFR in invasive breast cancer cells, we speculated that AnxA6-depletion in these cells might affect their response to EGFR-targeted TKIs." (PMID 24354805, 2013). "In this study, we investigated the contribution of AnxA6 in the activity of EGFR in invasive breast cancer cells and examined whether the expression status of AnxA6 influences the response of these cells to EGFR-targeted tyrosine kinase inhibitors (TKIs) and/or patient survival." (PMID 24354805, 2013). "Similarly, in a series of 154 women with invasive breast cancer, EGFR and pEGFR proteins were found in 11.3% and 35.7% of patients, respectively, and univariate and multivariate analysis showed that the EGFR/pEGFR phenotype was significantly associated with poor overall survival." (PMID 23819610, 2013). "In this study, we have shown that CA XII is frequently expressed in invasive breast carcinoma, where expression is strongly associated with several good prognostic parameters, including low tumour grade, ER-positive status, EGFR-negative status, and absence of necrosis." (PMID 12671706, 2003). "As a member of the human epidermal growth factor receptor (EGFR) family, HER2 plays a crucial role in the development of invasive breast cancer through its overexpression." (PMID 38248392, 2023). "Lastly, protein expression of the ANXA6 gene (mutated only in two patients with a CR) is required for membrane localization of activated EGFR and persistent activation of MAP kinaseERK1/2 and PI3K/Akt pathways in invasive breast cancer cells." (PMID 34791836, 2022). "The correlation between EGFR expression and FGF2 and FGFBP1 gene expression levels in breast invasive carcinoma subtypes with purity adjustment was statistically significant in its positive correlation in all BRCA, except for BRCA-Her2." (PMID 36430763, 2022). "Epidermal growth factor receptor (EGFR) signalling is a highly regulated process with a tight balance between receptor activation and inactivation in invasive breast carcinomas (IBCs) particularly in triple-negative carcinomas (TNC)." (PMID 32377505, 2020). "A previous study has identified that CTEN expression correlated with high EGFR and HER2 expression in invasive breast cancer." (PMID 29137409, 2017). "Based on gene expression profiling studies, invasive breast cancer can be divided into several subtypes: the basal-like, characterised by the expression of the CK5/6 and or EGFR, the luminal ER-positive groups, and a HER2 overexpressing group." (PMID 17088909, 2006). "Consistent findings were obtained as greater than 70% of invasive breast carcinomas expressed moderate to high levels of phosphorylated PDK-1, AKT, p70S6K, and EGFR." (PMID 16288304, 2005). "For example, immunohistochemistry staining analysis of 89 invasive breast cancer tissues and six normal mammary tissues found that more than 70% of invasive breast cancer tissues expressed high levels of phosphorylated PDK-1, AKT, p70S6K, and EGFR, relative to normal mammary tissues." (PMID 34571875, 2021). "Sustained activation of ErbB/Her2 and EGFR via thrombin-cleaved PAR-1 signaling was identified in invasive breast cancer but not in normal mammary epithelial cells." (PMID 29291033, 2017).
invasive breast carcinoma (continued). "Therefore, the optimal combination of membrane-expressed proteins to target by molecular imaging seemed to consist of CD44v6, GLUT1, EGFR, HER2, and IGF1-R by which about 80% of invasive breast cancers are predicted to be detectable." (PMID 22695343, 2012). "Furthermore it had been shown that proteolytic activation of PAR1 by thrombin induces persistent transactivation of EGFR and ErbB2/HER2 in invasive breast carcinoma." (PMID 19538737, 2009). "Nieto and coworkers also studied EGFR and pEGFR expression in invasive breast cancer, but they failed to attribute any prognostic value to pEGFR expression." (PMID 18522728, 2008). "Although our study has some limitations, such as its retrospective design and relatively small number of studied patients, the data obtained indicate that EGFR and CD44 could serve as useful biomarkers for better determination of the prognosis of invasive breast cancer." (PMID 25429827, 2015). "However, expression of EGFR and MMP-1 demonstrate a significant trend towards co-occurrence (p < 0.001), suggesting that this pathway may be maintained in invasive breast cancers." (PMID 26215578, 2015).
paronychia (62 papers, 2010 to 2026). An acute or chronic infection of the soft tissues around the nail. "Overall, all-grade TRAEs were very common, with diarrhea (66.8%), rash (66.7%), and paronychia (42.0%) being the most frequent, consistent with the typical toxicity spectrum of EGFR inhibitors targeting classical mutations." (PMID 41487495, 2025). "Compared with first-generation EGFR-TKIs, dacomitinib was associated with increased toxicity of diarrhea, rash, stomatitis, and paronychia." (PMID 37840124, 2023). "The side effects are associated with the unique properties of this drug as rash, paronychia, stomatitis, pruritis, and diarrhea resulting from EGFR inhibition while MET inhibition is associated with hypoalbuminemia and peripheral edema." (PMID 37880647, 2023). "AEs traditionally associated with EGFR inhibition included paronychia in 22 patients (49%), pruritus in 14 patients (31%), stomatitis in 12 patients (27%) and diarrhea in 10 patients (22%)." (PMID 37710001, 2023). "The chemotherapy-associated paronychia is a unique paronychia subtype due to various chemotherapeutics, most commonly epidermal growth factor receptor inhibitors and taxanes." (PMID 36407642, 2022). "This study revealed a significantly greater risk of serious dermatitis or paronychia with EGFR inhibitors, cetuximab and panitumumab." (PMID 35954563, 2022). "Paronychia (all grades) associated with EGFR-TKIs use is seen in 17–33%, 33%, 56%, and 35% of patients treated with gefitinib, erlotinib, afatinib, and osimertinib, respectively." (PMID 33466795, 2021). "Secondary bacterial (S. aureus) or fungal (Candida albicans) infection is common in paronychia associated with EGFR inhibition." (PMID 20680104, 2010). "Similarly, EGFR-targeting BsAbs like amivantamab have been associated with dermatologic toxicities, including rash and paronychia, reflective of EGFR’s physiological role in maintaining skin homeostasis." (PMID 40565299, 2025). "EGFR inhibitors are known to cause paronychia in 10%–15% of users." (PMID 34844792, 2022). "The disproportional RORs of paronychia obtained suggests that these four EGFR-TKIs may increase the risk of nail disorder." (PMID 32179761, 2020). "Compared with prior reports, this case's toe predominance contrasts with the predominantly finger (especially thumb) involvement noted in a 2022 meta-analysis, where paronychia was observed in 17.4% of patients receiving EGFR inhibitors." (PMID 40656293, 2025). "As EGFR is involved in regulating keratinocyte growth and differentiation, the most common dAEs of EGFR inhibitors include xerosis, pruritus, acneiform eruptions, and paronychia." (PMID 41216299, 2025). "Our research summarizes the best evidence for preventing and managing epidermal growth factor receptor inhibitors induced by paronychia in cancer patients." (PMID 40297810, 2025). "In this case, the presentation of toe-predominant paronychia at four weeks is atypical, as EGFR inhibitor-related paronychia commonly involves the thumbs and tends to emerge after six to eight weeks of therapy." (PMID 40656293, 2025). "For instance, agents such as EGFR inhibitors commonly induce dermatologic toxicities—including rash, dry skin, and paronychia—due to interference with EGFR signaling in normal skin cells." (PMID 40510154, 2025). "Common cutaneous side effects of EGFR inhibitors are acne‐like eruptions, xerosis, and paronychia, which can significantly reduce patients' quality of life." (PMID 40405694, 2025). "Causality assessments strongly support a link between dacomitinib and the observed paronychia, consistent with its mechanism of EGFR inhibition, which disrupts nail matrix cell proliferation and induces sterile inflammation." (PMID 40656293, 2025). "EGFR-TKI monotherapy is associated with less toxicity, with the most common adverse events being rash, stomatitis, paronychia, dry skin, and constipation." (PMID 39533233, 2024).
paronychia (continued). "The most common AEs of EGFR-TKIs, including skin toxicities, paronychia, mucositis, and diarrhea, were analyzed." (PMID 38194721, 2024). "The mechanisms underlying EGFR-TKI-induced skin disorders, such as paronychia, involve decreased keratinocyte proliferation and increased keratinocyte differentiation at the epidermis, resulting in impaired skin barrier function." (PMID 36637703, 2023). "Skin reactions are common adverse reactions to anti-EGFR therapy, reported in up to 45–100% of patients, including acneiform rash, dry skin, and paronychia." (PMID 36980549, 2023). "Compared with the first-generation EGFR-TKIs, afatinib has a higher incidence of stomatitis, diarrhea, and paronychia among all grades of AEs, and the incidence of rashes is similar." (PMID 37228701, 2023). "The key TRAEs of EGFR-TKIs include diarrhea, rash/acne, stomatitis, and paronychia, some of which appear to be more pronounced with afatinib." (PMID 38067272, 2023). "In particular, anti-epidermal growth factor receptor (EGFR) antibody drugs, which target EGFR, can cause the development of various skin disorders, such as acneiform rash, dry skin, and paronychia, because EGFR is also expressed in normal skin." (PMID 36045384, 2022). "For example, diarrhea, acneiform skin rash, and paronychia are the commonest side effects of EGFR-TKIs." (PMID 33466795, 2021). "Rash, paronychia, and diarrhea were the most common AEs reported with first- and second-generation EGFR-TKIs." (PMID 33466795, 2021). "Skin disorders are the commonest EGFR-TKI-associated AE and include rashes, such as acne, dry skin, and paronychia." (PMID 33466795, 2021). "The nail toxicity reported to FAERS with EGFR-TKIs included paronychia, onycholysis, and nail disorder." (PMID 32179761, 2020). "The common cutaneous reactions to EGFR inhibitors are labeled as the PRIDE syndrome (papulopustules and/ or paronychia, regulatory abnormalities of hair growth, itching, dryness due to the epidermal growth factor receptor inhibitors)." (PMID 27974909, 2016). "Most instances of paronychia related to EGFR TKI therapy are mild, but in clinical trials of afatinib, treatment-related paronychia led to dose reductions in 14% of patients." (PMID 29670808, 2016). "Paronychia: 15% to 20% of patients treated with EGFR inhibitors develop a painful paronychia that can become secondarily infected." (PMID 29152401, 2016). "If patients experience grade 3 paronychia (severe), the EGFR TKI should be discontinued until symptoms resolve." (PMID 29670808, 2016). "Paronychia occurs in approximately 50% of Asian patients treated with EGFR antibodies or TKIs." (PMID 40888993, 2025). "PCR-based EGFR mutation profiling revealed the tumor harbored the EGFRΔ19del mutation, leading to treatment with afatinib from August 2023 until March 2025, when therapy was discontinued due to grade I–II rash and grade III paronychia." (PMID 41439947, 2025). "Furthermore, regardless of gender, age, BMI, primary tumor site, recurrence, composite score, skin response, or paronychia, only the first-line treatment being an anti-EGFR inhibitor administered for mCRC had a significant influence on OS and PFS." (PMID 36980549, 2023). "Moreover, EGFR inhibitors favor the occurrence of nail pathology (e.g., paronychia), problems with hair (folliculitis, follicular necrosis, alopecia), and mucosal changes." (PMID 37686523, 2023). "The drugs most often implicated in these effects were epidermal growth factor receptor (EGFR) inhibitors, represented by panitumumab, gefitinib, and erlotinib, responsible for 50% of ungual changes (paronychia, periungual granulomas, onycholysis, onychodystrophy, and onychocryptosis)." (PMID 34844792, 2022). "Dermatologic toxicities such as acneiform rash, dry skin, pruritus, erythema, and paronychia have been reported in more than 90% patients receiving anti-EGFR monoclonal antibodies for the treatment of mCRC, although the majority of these toxicities are of mild grade." (PMID 34830870, 2021).